IGF1 (insulin like growth factor 1)
Diseases named in the same sentence as IGF1 in open-access papers (continued):
Sharing a sentence is not in itself a finding about the gene and the disease.
Gonadotropin deficiency (2 papers, 2016 to 2024). A reduced ability to secrete gonadotropins, which are protein hormones secreted by gonadotrope cells of the anterior pituitary gland, including the hormones follitropin (FSH) and luteinizing hormone (LH). "The independent factors associated with mortality were the last IGF1 level/last random GH level, absence of surgery, gonadotropin deficiency, and age." (PMID 38449845, 2024).
Growth hormone-producing adenomas (2 papers, 2019 to 2020). "This could be overlooked as IGF-1 hypersecretion resulting in smaller vessel as an explanation for the vasculature differences between NF-PitNETs and somatotrophinomas, a somewhat paradoxical speculation with the recognised angiogenic properties of IGF-1." (PMID 32946040, 2020).
haemoglobinopathy (2 papers, 2022 to 2023). "The panel has suggested an annual evaluation of IGF-1 in all patients with haemoglobinopathy, with subsequent stimulus test in case of abnormal IGF-1 value." (PMID 35407442, 2022). "There are no indications establishing the modality and frequency to assess GH/IGF-1 axis in adult subjects with haemoglobinopathy explicitly and univocally." (PMID 35407442, 2022).
hemophilia (2 papers, 2014 to 2022). Hemophilia is a genetic disorder characterized by spontaneous hemorrhage or prolonged bleeding due to factor VIII or IX deficiency. "Data presented suggest a primarily and predominantly disturbed biochemistry in OCD with differential regulation of IGF-1/IGF-1R, which is possibly more specific as the disturbed biochemistry in hemophilia, in which the whole inflammatory cascade is activated driven by the neutrophil influx." (PMID 24885831, 2014).
hemorrhage (2 papers, 2022 to 2025). Loss of blood from the vascular compartment to the exterior or into nonvascular body space as a result of rupture or severance of the blood vessels. "There is strong evidence that circulating IGF-1 deficiency is causally linked to the genesis of CMHs and larger intracerebral hemorrhages." (PMID 35356301, 2022). "Strategies to restore or mimic IGF-1 signaling may strengthen fragile cerebral vessels, enhancing resilience against hemorrhage." (PMID 41157242, 2025).
Hernia (2 papers, 2023 to 2024). "In vitro, the accelerated division and proliferation of fibroblasts and smooth muscle cells cultured with IGF-1 and the increase in cell size may be one of the factors contributing to the formation of hernia." (PMID 38591204, 2024).
hippocampal atrophy (2 papers, 2022 to 2023). "Previous studies have shown that lower IGF-1 concentrations were associated with hippocampal atrophy, areas vital for learning and memory." (PMID 35832183, 2022). "In a study on the relationship between IGF-1, cognitive function, and neuroimaging indicators in elderly hypertensive patients, IGF-1 deficiency was found to be associated with hippocampal atrophy." (PMID 37358957, 2023).
HIV encephalitis (2 papers, 2013 to 2015). "Immunohistochemistry of human brain tissues showed that nonparenchymal cells (vessels and meninges), as well as parenchymal microglia and macrophages were positive for IGF1, in both HIV encephalitis and control brains, while IGF2 was undetectable." (PMID 23497056, 2013).
Hypergonadotropic hypogonadism (2 papers, 2020 to 2023). Reduced function of the gonads (testes in males or ovaries in females) associated with excess pituitary gonadotropin secretion and resulting in delayed sexual development and growth delay. "Concerning pituitary hormones, he showed moderated prolactin elevation, hypergonadotropic hypogonadism, and low insulin-like growth factor 1 (IGF1) levels, which could be explained by CKD." (PMID 36334246, 2023).
hypospadias (2 papers, 2025). Hypospadias is the displacement of the urethral meatus on the ventrum of the penis. "Therefore, miR-210 can promote the development of hypospadias through insulin/IGF1 and hypoxia signaling." (PMID 39624466, 2025).
hypoxia (2 papers, 2016 to 2022). A decrease in the amount of oxygen in the body. "Both insulin and IGF-1 are known to play a significant role in the regulation of myelin synthesis, and treatment with IGF-1 has been shown to protect oligodendrocytes in animal models of excitotoxicity and cerebral hypoxia-ischemia." (PMID 30202553, 2016). "Our subsequent findings revealed that IGF-1 concentration was negatively correlated with AHI and ODI scores and positively correlated with minimum oxygen saturation, demonstrating that sleep hypoxia and sleep structure disorder have a significant impact on IGF-1 concentration." (PMID 36120463, 2022).
Hypsarrhythmia (2 papers, 2025). Hypsarrhythmia is abnormal interictal high amplitude waves and a background of irregular spikes. "Preclinical trials employing IGF-1-derived tripeptides have demonstrated efficacy in reducing spasms and hypsarrhythmia through IGF-1 pathway activation." (PMID 40371354, 2025). "Preclinical animal studies demonstrate the therapeutic potential of an IGF-1-derived tripeptide treatment, which shows significant anticonvulsant effects and suppresses hypsarrhythmia on EEG." (PMID 40371354, 2025). "In animal models, IGF-1 administration effectively eliminates both spasms and hypsarrhythmia, indicating its potential utility as both a therapeutic agent and disease severity biomarker." (PMID 40371354, 2025). "We analyzed serum IGF-1, IGFBP-3 levels, and IGF-1/IGFBP-3 ratios in the hypsarrhythmia subgroup before and after ACTH therapy." (PMID 40371354, 2025). "In this study, among IESS patients in the hypsarrhythmia subgroup, those with higher baseline serum levels of IGF-1, IGFBP-3, and their ratio prior to treatment demonstrated a significantly better response to ACTH therapy." (PMID 40371354, 2025). "Serum IGF-1 levels may serve as a predictor of therapeutic response in IESS patients exhibiting hypsarrhythmia on EEG." (PMID 40371354, 2025). "For instance, patients exhibiting low baseline IGF-1 levels combined with hypsarrhythmia EEG patterns might benefit from early intensive interventions, such as ACTH dose escalation or combination therapy with vigabatrin." (PMID 40371354, 2025). "We compared the serum IGF-1 and IGFBP-3 levels, as well as the IGF-1/IGFBP-3 ratio, between the hypsarrhythmia and non-hypsarrhythmia groups before ACTH treatment." (PMID 40371354, 2025). "The hypsarrhythmia population exhibited significantly lower serum IGF-1 levels and IGF-1/IGFBP-3 ratios (p < 0.05) compared to the non-hypsarrhythmia population." (PMID 40371354, 2025). "Our findings demonstrate that serum IGF-1, IGFBP-3 levels, and their ratio correlate with both hypsarrhythmia severity and short-term ACTH response in IESS patients." (PMID 40371354, 2025). "This study examined how serum IGF-1 levels, IGFBP-3 levels, and their ratio relate to EEG hypsarrhythmia and ACTH therapy response in IESS patients, demonstrating the potential clinical value of peripheral IGF-1." (PMID 40371354, 2025). "Hypsarrhythmia inversely correlated with both serum IGF-1 levels and IGF-1/IGFBP-3 ratios, consistent with previous findings, suggesting that decreased ratios may indicate reduced bioactive IGF-1, thereby worsening hypsarrhythmia." (PMID 40371354, 2025). "Within the hypsarrhythmia population, responders (n = 9) showed higher IGF-1, IGFBP-3 levels, and IGF-1/IGFBP-3 ratios than non-responders (n = 5) before ACTH treatment (p < 0.05)." (PMID 40371354, 2025).
inflammatory breast carcinoma (2 papers, 2021 to 2023). An advanced, invasive breast adenocarcinoma characterized by the presence of distinct changes in the overlying skin. "In spite of the weak IGF binding, CCN6 is implicated in inflammatory breast cancer as knock down leads to IGF1 induced tumorigenesis and cell growth, and CCN6 is lost in more than 80% of inflammatory breast cancers." (PMID 37245184, 2023). "Although its IGF binding ability is lower than that of full-length IGFBPs, the IGFBP domain of CCN3 reduces activation of IGF1-IGF1R signaling in inflammatory breast cancer, and downregulation of CCN6 enhances the effects of IGF1 on growth, motility, and invasiveness." (PMID 33833779, 2021).
inner ear disease (2 papers, 2014 to 2021). "The application of insulin-like growth factor 1 (IGF-1) to the round window membrane (RWM) is an emerging treatment for inner ear diseases." (PMID 34199327, 2021). "This suggests that USMB-mediated IGF-1 treatment is an effective therapy for inner ear disease and has high potential for clinical application in the future." (PMID 34199327, 2021). "The successful application of IGF-1 to the treatment of aminoglycoside-induced mammalian vestibular HC damage suggested that IGF-1 was an effective molecule for use in inner ear disorders." (PMID 25309440, 2014). "Accordingly, application of ultrasound-irradiated IGF-1-loaded MBs via a transcanal approach may be a more practical and effective treatment modality for inner ear diseases and needs to be further investigated." (PMID 34199327, 2021).
ischemic cardiomyopathy (2 papers, 2009 to 2010). Ischemic cardiomyopathy is a cardiomyopathy in which a weakness in the muscle of the heart due to inadequate oxygen delivery to the myocardium with coronary artery disease being the most common cause. "The expression of IGF-1 was increased in the remote, border and infarction zones in dogs with ischemic cardiomyopathy, and also increased in the myocardium of dogs with tachycardiomyopathy." (PMID 19818143, 2009). "In this study, we show that the gene expressions of cyclins B, D1, D3 and E are increased in ischemic cardiomyopathy in relation to increased IGF-1 and IGF-1R expressions and echocardiographic measures of wall thickness but are not increased in tachycardiomyopathy." (PMID 19818143, 2009). "In the present study, there was an increased expression of IGF-1R in ischemic cardiomyopathy but not in tachycardiomyopathy, indirectly suggesting that parallel increased expressions of IGF-1 and its receptor are only to be observed in myocardial injury with a hypertrophic response." (PMID 19818143, 2009). "Administration of synthetic GSH, such as hexarelin and GHRP-6, have also demonstrated improvements in patients and animals with ischemic cardiomyopathy or dialated cardiomyopathy (DCM), independent of IGF-1." (PMID 21286280, 2010).
kidney stones (2 papers, 2013 to 2022). "This case is in full accordance with a primary role of IGF1-mediated, PTH-independent increase in calcitriol synthesis resulting in hypercalciuric kidney stones." (PMID 24616756, 2013).
learning disabilities (2 papers, 2023). "Most of these patients later developed learning disabilities (67% vs. 5.8%, p=0.013) and fine motor deficits (75% vs. 25%, p=0.000) at the time of testing compared to those with normal and low serum levels of IGF-1." (PMID 36843696, 2023). "From our RNA-Seq data, among the 11 differentially regulated high-confidence ASD risk genes, there are few, which display learning disability phenotypes, which include GRIA1, GRID2, and IGF1." (PMID 37486945, 2023).
lipidosis (2 papers, 2022 to 2023). "Beyond our hypothesis, effects of treatment were clearly multifactorial and, in part, appeared to be associated with an increased expansion of VAT involving the modulation of growth factors such as IGF1 and FGF1, ECM organization through TIMP4, and lipidosis." (PMID 35737302, 2022).
liposarcoma (2 papers, 2017 to 2018). A usually painless malignant tumor that arises from adipose tissue. "We provide evidence that IGFBP5 can acts as a tumor suppressor in liposarcoma cells in an IGF-1 dependent manner; and selinexor can markedly up-regulate the expression of this tumor suppressor protein." (PMID 27893412, 2017).
lobular carcinoma (2 papers, 2018 to 2023). "To further study IGF-1 expression in lobular carcinoma and its correlation with clinicopathological features, we generated a TMA containing 54 ILC and 52 IDC samples." (PMID 30337563, 2018).
lymphocytic hypophysitis (2 papers, 2017 to 2022). "Our IGF-1 and free T4 results are also consistent with another histopathologically-confirmed example of canine lymphocytic hypophysitis." (PMID 28241874, 2017).
manic episode (2 papers, 2020 to 2024). "In order to reveal this point, we kept cortisol level, BMI and age under control statistically in the groups and we found that GDNF and Nrn 1 levels were significantly lower while IGF-1 levels were significantly higher in bipolar manic episode patients compared to the control group." (PMID 32283906, 2020).
mantle cell lymphoma (2 papers, 2014 to 2017). Mantle cell lymphoma is a rare form of malignant non-Hodgkin lymphoma affecting B lymphocytes in the lymph nodes in a region called the ``mantle zone''. "In hematopoietic malignancies, a critical role was shown of the IGF-1/IGF-1R signaling pathway for proliferation and survival in multiple myeloma (MM) and mantle cell lymphoma (MCL)." (PMID 24489919, 2014).
measles (2 papers, 2017 to 2024). A highly contagious viral infection caused by the measles virus. "It is currently unknown whether elevated osteoclast-IGF1 and osteocyte senescence are central factors in the development of pagetic lesions in Paget’s disease due to causes such as mutations in p62 or non-measles environmental factors." (PMID 38457001, 2024). "Both CSF insulin and IGF-1 levels were positively correlated with serum measles immunoglobulin G (IgG)." (PMID 28954393, 2017). "Further studies will reveal whether there are possible pathogenetic relations between IGF-1, measles IgG titers and tau protein in SSPE." (PMID 28954393, 2017).
mucositis (2 papers, 2016 to 2020). Mucositis is inflammation and damage of the mucous membranes lining the mouth and other parts of the gastrointestinal (GI) tract. "In animal models, IGF-1 administration has been shown to limit mucositis, enhance mucosal repair and reduce bacterial translocation following irradiation or chemotherapy-induced damage." (PMID 32793242, 2020).
myotonic dystrophy type 1 (2 papers, 2022 to 2024). Steinert disease, also known as myotonic dystrophy type 1, is a muscle disease characterized by myotonia and by multiorgan damage that combines various degrees of muscle weakness, arrhythmia and/or cardiac conduction disorders, cataract, endocrine damage, sleep disorders and baldness. "IGF-1 has been investigated in clinical trials for the treatment of Duchenne muscular dystrophy (NCT01207908) and myotonic dystrophy type 1 (NCT00577577 and NCT00233519)." (PMID 39639374, 2024).
myxoma (2 papers, 2020 to 2022). A benign soft tissue neoplasm characterized by the presence of spindle and stellate cells, lobulated growth pattern, and myxoid stroma formation. "Furthermore, IPA further revealed that the dysregulated genes in myxoma-derived CSCs are components of several canonical pathways such as HGF and IGF-1 signalling, telomerase signalling, stem cell pluripotency, and stem cell signalling among others." (PMID 32330934, 2020).
nephritis (2 papers, 2014 to 2022). Inflammation of renal tissue. "IGF1 is an important growth factor that maintains the structure and function of nephritis and plays a vital role in the pathology of DKD." (PMID 36160448, 2022).
obsessive-compulsive disorder (2 papers, 2025 to 2026). A disorder characterized by the presence of persistent and recurrent irrational thoughts (obsessions), resulting in marked anxiety and repetitive excessive behaviors (compulsions) as a way to try to decrease that anxiety. "Research on IGF levels in obsessive compulsive disorder (OCD) is more limited, but preliminary findings suggest altered IGF-1 reflecting underlying neuroplasticity deficits." (PMID 40141202, 2025).
obstructive jaundice (2 papers, 2016 to 2026). A finding indicating increased bilirubin levels in the blood and urine, due to intrahepatic or extrahepatic obstruction of the biliary system. "IGF-1 was used in experimental obstructive jaundice to determine the apoptosis and ductular proliferation of liver tissue." (PMID 27540507, 2016).
osteonecrosis (2 papers, 2009 to 2021). A none disease characterized by death of bone tissue due to a lack of blood supply. "We found a heterozygous mutation (c.15+3G>A) in IGF1 in this family, which could be related to osteonecrosis of the femoral head." (PMID 33429739, 2021). "Genes related to osteonecrosis of the femoral head were analyzed by full whole exome sequencing (WES), which revealed insulin-like growth factor 1 (IGF1) as a potential marker for genetic counseling and molecular diagnosis of osteonecrosis of the femoral head." (PMID 33429739, 2021).
Paget disease (2 papers, 2023 to 2024). A malignant neoplasm composed of large cells with large nuclei, prominent nucleoli, and abundant pale cytoplasm (Paget cells). "Immunohistochemical studies of bones from Paget’s disease patients showed that pagetic osteoclasts contained abundant platelet-derived growth factor, transforming growth factor-β and IGF1, as well as IL-6." (PMID 38457001, 2024). "Abnormal osteoclasts in Paget’s disease secrete abundant IGF1, which enhances osteocyte senescence, contributing to lesion formation." (PMID 38457001, 2024). "Recent data suggest that osteocytes contribute to lesion formation in Paget’s disease by responding to high local IGF1 released from abnormal osteoclasts." (PMID 38457001, 2024). "Osteoclast-secreted IGF1 in Paget’s disease could thus act on nearby osteocytes to induce senescence and increase local RANKL." (PMID 38457001, 2024). "We hypothesize that a local subset of osteoclasts in Paget’s disease patients may undergo senescence due to exposure to high local levels of osteoclast-IGF1, forming a niche that activates precursors to increase pagetic-OCL formation." (PMID 38457001, 2024). "In future studies, pagetic bone samples from patients with Paget’s disease and from mouse models could be stained for osteocyte morphology and expression of RANKL, sclerostin and senescence markers and for IGF1 in osteoclasts." (PMID 38457001, 2024).
pancreatic diseases (2 papers, 2016 to 2023). "The IGF-1/IGFBP-2 ratio turned out to be a good marker of pancreatic diseases, but insufficient for the purpose of CP and PDAC differentiation." (PMID 37373743, 2023). "However, our present results confirm that the IGF-1/IGFBP-2 ratio can only differentiate general pancreatic diseases from the group of healthy patients." (PMID 37373743, 2023). "Recently, a three-marker signature based on levels of CA19-9, IGF-1, and albumin has shown a sensitivity of 93.6% and specificity of 95% when differentiating PDAC patients from other pancreatic diseases." (PMID 27689078, 2016).
pelvic organ prolapse (2 papers, 2020 to 2025). Abnormal descent of a pelvic organ resulting in the protrusion of the organ beyond its normal anatomical confines. "This study was carried out to observe the impact of insulin-like growth factor-1 (IGF-1) on human vaginal fibroblasts (HVFs) in the context of pelvic organ prolapse (POP) and to explore its effects on mitogen-activated protein kinases (MAPK) and nuclear factor-κB (NF-κB) signaling pathways." (PMID 33336041, 2020).
pituitary infarction (2 papers, 2011 to 2025). "Historically, cases of pituitary infarction have demonstrated regression of PDR in some patients, thereby implicating growth hormone (GH) and IGF-1 in the progression of DR." (PMID 40362202, 2025).
pituitary stalk interruption syndrome (2 papers, 2008 to 2019). "In their retrospective study, Delecroix and colleagues evaluated blood 25(OH)D, 1,25(OH)2D, GH and IGF-1 levels at diagnosis in 50 GHD patients due to pituitary stalk interruption syndrome (PSIS)." (PMID 30885216, 2019).